FOXP3 (forkhead box P3)
Diseases named in the same sentence as FOXP3 in open-access papers (continued):
Sharing a sentence is not in itself a finding about the gene and the disease.
mycosis fungoides (3 papers, 2011 to 2024). Classical mycosis fungoides is the most common type of mycosis fungoides (MF), a form of cutaneous T-cell lymphoma, and is characterized by slow progression from patches to more infiltrated plaques and eventually to tumors. "IL: interleukin; MFME: mycosis fungoides microenvironment; CD: cluster of differentiation; FOXP3: forkhead box P3." (PMID 37900389, 2023). "Mycosis fungoides (MF) with early or infiltrated plaques have significantly higher numbers of FOXP3+ Tregs than CTCL unspecified or advanced MF with tumors or transformation to large cell lymphoma." (PMID 22151904, 2011). "Based on previous studies, it appears that a high quantity of FoxP3+ cells in the TME has a positive impact on survival outcomes in certain extranodal TCLs, such as mycosis fungoides (MF), unspecified cutaneous TCLs, and extranodal NK/T lymphomas (ENKTLs)." (PMID 39682197, 2024).
nasal polyps (3 papers, 2009 to 2024). "Here we demonstrate for the first time that the mTOR signaling pathway is associated with Foxp3+ Tregs insufficiency in nasal polyps." (PMID 19250527, 2009). "Given the critical role of Foxp3+ Tregs in immune tolerance, further investigation of the signaling pathways underlying Foxp3+ Treg enrichment in nasal polyps is of significant interest." (PMID 19250527, 2009). "Significantly increased infiltration of pmTOR+ inflammatory cells and decreased infiltration of Foxp3+CD4+ Tregs into nasal polyps was observed, with an inverse association." (PMID 19250527, 2009). "Alternatively, we used rapamycin, a specific inhibitor of mTOR, in this study, and provide evidence that blocking the mTOR signal is associated with Foxp3 expression and Foxp3+ Treg expansion in cultured nasal polyps." (PMID 19250527, 2009). "Our findings are, therefore, important because they demonstrate the possible association between the mTOR signaling pathway and Foxp3+ Treg expansion in nasal polyps, which may possess clinical potential for developing strategies of treating nasal polyps." (PMID 19250527, 2009). "Therefore, our results provide evidence that rapamycin stimulation is associated with Foxp3 mRNA expression in nasal polyps." (PMID 19250527, 2009). "Our results provide the first evidence that the activation of the mTOR signaling pathway may play an important role in Foxp3+ Tregs insufficiency in nasal polyps and that blocking the mTOR signal with rapamycin is associated with Foxp3+ Treg expansion in situ." (PMID 19250527, 2009). "Therefore, our results raised the possibility that the mTOR signaling pathway may be associated with Foxp3+ Treg insufficiency in nasal polyps." (PMID 19250527, 2009). "To address this issue, we analyzed the protein expression of phosphorylated mTOR and Foxp3 in nasal polyps." (PMID 19250527, 2009). "More recently, a Th2-skewed eosinophilic inflammation with high levels of IL-5 and IgE was described in CRSwNP, and decreased Foxp3 mRNA was demonstrated in nasal polyps." (PMID 19250527, 2009). "Subsequently, we examined the levels of T-bet, GATA-3, Foxp3, and RORγt mRNA expression in cultured nasal polyps." (PMID 19250527, 2009). "Our results indicate that the number of Foxp3+CD4+ Tregs negatively correlated with the number of pmTOR+ inflammatory cells in nasal polyps (b = -0.74, P < 0.01)." (PMID 19250527, 2009). "We attempted to investigate the tissue expression of phosphorylated mammalian target of rapamycin (pmTOR) and infiltration of Foxp3+ Tregs in 28 nasal polyps and 16 controls by histological staining." (PMID 19250527, 2009). "In the tissue culture system, we detected significantly elevated Foxp3 expression and IL-10 production, as well as an increased percentage of Foxp3+ Tregs in nasal polyps after blocking the mTOR signaling pathway with rapamycin." (PMID 19250527, 2009). "After treatment with rapamycin, a significant increase in the frequencies of CD4+CD25+ cells and Foxp3+CD4+ Tregs in nasal polyps was found compared to untreated nasal polyps (P < 0.05 by the paired t-test)." (PMID 19250527, 2009). "For intragroup comparison, we found the percentages of CD4+CD25+ and Foxp3+CD4+ cells to be significantly decreased in nasal polyps compared to the control (P < 0.05 by the unpaired t-test)." (PMID 19250527, 2009). "In order to evaluate the frequency of Foxp3+ Tregs in nasal polyps after rapamycin treatment, we examined CD4, CD25, and Foxp3 biomarkers in isolated cells from nasal polyps by flow cytometric analysis." (PMID 19250527, 2009). "After treatment with rapamycin, we found that the level of Foxp3 mRNA was increased by as much as 5.5-fold in nasal polyps, while the levels of T-bet and GATA-3 mRNA decreased, revealing an inverse inter-modulation tendency." (PMID 19250527, 2009).
nasal polyps (continued). "We consistently found that the percentage of Foxp3+ Tregs was decreased in nasal polyps compared to the control tissues, confirming the possible role of Foxp3+ Tregs in the immune imbalance of nasal polyps." (PMID 19250527, 2009). "The number of Foxp3+CD4+ cells decreased significantly in nasal polyps compared to control nasal tissues (P < 0.05 by the unpaired t-test)." (PMID 19250527, 2009). "For intragroup comparison, we observed a significant elevation of T-bet and GATA-3 mRNA, but a significant reduction of Foxp3 mRNA in nasal polyps compared to the control mucosa (P < 0.05 by the unpaired t-test)." (PMID 19250527, 2009). "Since the functional development of T cells is regulated by specific transcription factors, we quantified the levels of T-bet, GATA-3, Foxp3, and RORγt mRNA in rapamycin-stimulated nasal polyps by real time RT-PCR." (PMID 19250527, 2009). "In our previous reports, we provided evidence that the level of Foxp3 protein and the number of Foxp3+ Tregs decreased significantly in nasal polyps." (PMID 19250527, 2009). "Elevated Foxp3 protein (by 3.3-fold) was consistently observed in nasal polyps after rapamycin administration by western blot analysis." (PMID 19250527, 2009). "To determine the possible role of mTOR signaling in Foxp3+ Treg insufficiency in nasal polyps, we investigated the percentages of Foxp3+ Tregs and cytokine profiles in a tissue culture system after treatment with rapamycin." (PMID 19250527, 2009). "Together, these results provide evidences that decreased infiltration of Foxp3+ Tregs or Treg insufficiency is essential for dysregulation of the Th1/Th2 cytokine network in nasal polyps." (PMID 19250527, 2009). "We hypothesized that a hyper-activated mTOR signaling pathway contributes to Foxp3+ Treg insufficiency in nasal polyps." (PMID 19250527, 2009). "Our findings suggest that the mTOR signaling pathway may play an important role in Foxp3+ Treg insufficiency and provide some clues about the immunomodulation in nasal polyps." (PMID 19250527, 2009). "In order to evaluate whether Foxp3+CD4+ cells were associated with pmTOR+ inflammatory cells, we investigated the quantitative relationship between the numbers of pmTOR+ inflammatory cells and Foxp3+ CD4+ Tregs in nasal polyps by linear regression." (PMID 19250527, 2009). "Decreased infiltration of Foxp3+ T regulatory cell (Treg) is considered to be critical for the Th1/Th2 dysregulation of nasal polyps, while the cellular mechanism underlying Foxp3+ Treg insufficiency is currently not well defined." (PMID 19250527, 2009). "In order to evaluate the possible association between inhibition of mTOR signaling and Foxp3+ Treg expansion, we investigated a series of proteins, including PTEN, PI3K, pAkt, pmTOR, p4E-BP1, T-bet, GATA-3, and Foxp3 in rapamycin-stimulated nasal polyps by western blot analysis." (PMID 19250527, 2009). "Inhibition of the mTOR signaling pathway may be helpful for enhancement of Foxp3+ Treg expansion, as well as modulation of T cell phenotype imbalances in nasal polyps." (PMID 19250527, 2009). "Interestingly, our results, presented characteristically high levels of T-bet/GATA-3 mRNA and low levels of Foxp3 mRNA in nasal polyps, which is consistent with previous reports." (PMID 19250527, 2009). "Furthermore, Foxp3 expression was significantly upregulated (3.3-fold in nasal polyps and 2.3-fold in control tissues; P < 0.05 by the paired t-test) after rapamycin stimulation, while T-bet and GATA-3 expression decreased correspondingly (P < 0.05 by the paired t-test)." (PMID 19250527, 2009). "We also evaluated the effects of rapamycin stimulation on the percentages of Foxp3+ Tregs and on the phosphatase and tensin homologue deleted on chromosome 10 (PTEN)/PI3K-Akt-mTOR signaling pathway in cultured nasal polyps." (PMID 19250527, 2009). "In order to more precisely identify Foxp3+ Tregs in nasal polyps, we simultaneously evaluated CD4 and Foxp3 by double immunofluorescence staining." (PMID 19250527, 2009).
nasal polyps (continued). "The role of Tregs in CRS remains complex, with studies reporting that CD25+/CD4+ FOXP3+ T cells are significantly higher in CRS with nasal polyps than in CRS without nasal polyps." (PMID 38812518, 2024). "Moreover, the results for CD4, CD25, and Foxp3 biomarkers in isolated T cells by flow cytometry showed that the frequencies of CD4+CD25+ cells and Foxp3+CD4+ Tregs significantly increased in nasal polyps after rapamycin stimulation." (PMID 19250527, 2009). "Given that Foxp3 is also expressed by other non-CD4+ T cells, we evaluated the change in the Foxp3+ Treg population in nasal polyps by flow cytometric analysis to further support our hypothesis." (PMID 19250527, 2009).
neuropathy (3 papers, 2015 to 2017). A disorder affecting the nervous system that manifests with pain, tingling, numbness, and/or muscle weakness. "All these suggest that neuropathy and imbalanced Foxp3/IL-17 immunology may contribute together to AML." (PMID 27016413, 2016).
oesophageal cancers (3 papers, 2015 to 2025). "Conversely, increased infiltration of FoxP3+ Tregs was found to be associated with improved OS in colorectal (OR 0.71, 95% CI 0.62 to 0.82, P = 0.01), head and neck (OR 0.69, 95% CI 0.50 to 0.95, P = 0.024), and oesophageal cancer (OR 0.51, 95% CI 0.33 to 0.79, P = 0.002)." (PMID 26462617, 2015).
oropharyngeal cancer (3 papers, 2018 to 2019). Carcinoma, predominantly squamous cell, arising from the epithelial cells of the oropharynx. "Regarding the prognostic value of Treg infiltration, the high infiltration of Foxp3 Tregs was associated with improved OS or RFS in both oropharyngeal cancer and HNSCC." (PMID 31510065, 2019).
pancreatic autoimmunity (3 papers, 2019 to 2024). "Importantly, mice with partial Foxp3 insufficiency developed early-onset lympho-proliferation and lethal autoimmune pancreatitis when PD-1 is deficient, which can be rescued by the transfer of PD-1-Foxp3+ Tregs." (PMID 34480337, 2021). "In the nonobese diabetic mouse model of type 1 diabetes (T1D), KLRG1 is expressed on Foxp3+ Treg cells in the pancreatic islets and plays a role in inhibiting pancreatic autoimmunity, resulting in a decrease in the proliferative and inhibitory functions of Foxp3+ Treg cells." (PMID 38898461, 2024).
Parkinson disease (3 papers, 2017 to 2021). A progressive degenerative disorder of the central nervous system characterized by loss of dopamine producing neurons in the substantia nigra and the presence of Lewy bodies in the substantia nigra and locus coeruleus. "Few reports suggested the relationship between FOXP3 expression with Parkinson and Huntington diseases." (PMID 34006632, 2021). "In the previous study, we reported that the protective role of bvPLA2 as a novel Foxp3+ Treg cell inducer in a mouse model of Parkinson’s disease." (PMID 28218721, 2017).
pemphigus (3 papers, 2013 to 2023). Pemphigus is a group of rare autoimmune diseases that cause blistering of the skin and mucous membranes (mouth, nose, throat, eyes, and genitals).This conditioncan occur at any age, but often strikes people in middle or older age. "We examined expression of the transcription factor FOXP3, which serves as important master regulator of regulatory T cell (Treg) differentiation and found that it was upregulated in pemphigus compared to controls." (PMID 34660634, 2021). "The second intriguing issue is that the number of Foxp3+ cells in BP was significantly smaller than that in pemphigus groups." (PMID 23970818, 2013).
penile cancer (3 papers, 2018 to 2024). A primary or metastatic malignant neoplasm that affects the penis. "An elevated presence of CD8+ T cells and forkhead box P3 (Foxp3)+ Tregs in the stroma of penile cancer suggests inefficient tissue infiltration, signifying an immune escape of tumor cells." (PMID 39690423, 2024). "Within the context of PSCC, compared with intratumor, CD8+ T cell and Foxp3+ regulatory T cell (Treg) numbers are much higher in the stroma of penile cancer, indicating aggregated but not efficiently infiltrating TILs; thus, penile cancer seems to be immune excluded." (PMID 36524123, 2022).
Peptic ulcer (3 papers, 2016 to 2024). The term peptic ulcer refers to acid peptic injury of the digestive tract, resulting in mucosal break reaching the submucosa. "In contrast, the proportion of FOXP3+ events among CD4+CD25hi cells was not significantly different with respect to peptic ulcer disease status among the infected group." (PMID 27014260, 2016).
periodontal disease (3 papers, 2014 to 2020). "Taken together, these results suggest that Foxp3/CD25 double-positive Treg cells may play a role in the downregulation of RANKL expression by activated lymphocytes in periodontal disease tissues." (PMID 24719884, 2014).
pituitary adenomas (3 papers, 2021 to 2023). "A high expression of CCL2, CXCL10, CX3CL1, with a low number of infiltrating FOXP3 T-cells and a high number of infiltrating CD4+ T-cells was detected in highly vascularized pituitary adenomas/PitNets." (PMID 36658300, 2023). "Meanwhile, M2 macrophages also take part in the neo-angiogenesis in pituitary adenoma/PitNets, together with B cells, CD4+ T-cells and Foxp3+ lymphocytes." (PMID 36658300, 2023). "Invasiveness has been associated with a higher CD8+ T cell count and a higher FOXP3:CD8 cell ratio, especially in non-functioning pituitary adenomas (NF-PitNETs)." (PMID 37958702, 2023).
pituitary tumor (3 papers, 2019 to 2024). A benign or malignant neoplasm affecting the pituitary gland. "Pituitary-specific deletion of AIP in mice led to increased infiltration of tumors with macrophages and FOXP3+Tregs, consistent with AIP-mutation-positive tumors in humans versus sporadic pituitary tumors." (PMID 38479600, 2024). "AIP-mutation positive pituitary tumors were associated with an altered tumor microenvironment including increased CD86+ macrophage and FOXP3+ Tregs infiltration, and upregulation of tumor-derived cytokine CCL5 (also known as RANTES)." (PMID 38479600, 2024). "Some recent studies reported significant infiltrates of natural killer (NK) cells and FOXP3+ T cells in the microenvironment of PIT1-positive pituitary tumors." (PMID 37958702, 2023). "In pituitary tumors with a Ki-67 ≥ 3%, lower CD8:CD4 and CD8:FOXP3 T cell ratios and higher levels of macrophages, T helper, FOXP3+, and B cells were reported." (PMID 37958702, 2023). "The pituitary tumors characterized by elevated expression of PD-L1 presented prevalent immune infiltrates of CD4+, CD8+, and FOXP3+ T cells, highlighting the ability of pituitary tumor-infiltrating immune cells to modulate the expression of immune checkpoint regulators." (PMID 37958702, 2023). "Further studies will be needed to reveal the functional role of FOXP3 in pituitary tumors and to see whether CCL5 is indeed involved in recruitment of T-reg cells in AIPpos pituitary tumors." (PMID 30867568, 2019).
pneumonitis (3 papers, 2007 to 2023). An inflammatory process affecting the lung parenchyma. "CD4+CD25+Foxp3+ T cells (Treg cells) and CD4+CD25+Foxp3+ CCR2-transfected T cells (CCR2-Treg cells) were transferred via retro-orbital injection into 12-week-old MRL/lpr mice at the early stage of pneumonitis and sialadenitis, and the pathological changes were evaluated." (PMID 17284325, 2007).
prostate adenocarcinoma (3 papers, 2022 to 2023). "Furthermore, to validate the correlation between ORC6 expression and Treg cell infiltration, IHC staining of FOXP3, which serves as a lineage specification factor of Treg cells, was performed in tumor samples from 19 patients with prostate adenocarcinoma." (PMID 36978046, 2023).
pulmonary hypertension (3 papers, 2018 to 2025). Increased pressure within the pulmonary circulation due to lung or heart disorder. "Another study showed that in pulmonary hypertension, FOXP3 has also been associated with promoting pulmonary angiogenesis and development." (PMID 38195465, 2024). "An increase in circulating CD8 + effector T cells and elevation in CD4 + FOXP3 + (Treg) cells in patients with PAH have been corroborated in genetic models of pulmonary hypertension." (PMID 30081463, 2018). "Impaired Treg function due to reduced FOXP3 level may contribute to pulmonary vascular remodelling and subsequent pulmonary hypertension." (PMID 38195465, 2024).
rectal tumor (3 papers, 2014 to 2024). "In conclusion, rectal tumors showing loss of HLA class I expression, Foxp3+ infiltration below median and weak HLA-G expression were related to a worse OS and DFS." (PMID 24997850, 2014). "In our study, FOXP3(r = 0.179), CD72(r = 0.155), RUNX1(r = 0.327), LAG3(r = 0.194), CTLA4(r = 0.236) have a positive correlation with AP3M2 in Colon Neoplasm, but no irrelevancy in rectal tumor." (PMID 38177168, 2024).
serous ovarian cancer (3 papers, 2013 to 2023). "Our study sought to investigate the association of tumor-infiltrating CD4+CD25+FOXP3+ Tregs, and other immune factors, with clinical outcome in serous ovarian cancer patients." (PMID 24244610, 2013). "In yet a more recent study, Milne and colleagues showed, in high grade serous ovarian cancer, that the count of intraepithelial cells singly stained for FOXP3+ was associated with greatly improved survival." (PMID 24244610, 2013). "In the present study, we found for the first time that CD4+CD25+FOXP3+ Tregs are associated with outcome specifically in serous ovarian cancer but only in the context of CD8+ T cells." (PMID 24244610, 2013). "A large mRNA expression profiling study in high-grade serous ovarian cancer found that patients with high tumor expression of FOXP3 had better survival (HR 0.93, 95% CI 0.89–0.97, p = 1.36E-03)." (PMID 36368129, 2023). "Another report implies that Foxp3+ regulatory cells are recruited to the tumor microenvironment of high grade serous ovarian cancer and act through immunomodulatory cytokines such as IL-10 and TGF-β." (PMID 34181334, 2021). "We performed immunofluorescence and quantification of intraepithelial tumor-infiltrating triple positive Tregs (CD4+CD25+FOXP3+), as well as CD4+CD25+FOXP3-, CD3+ and CD8+ T cells in tumor specimens from 52 patients with high stage serous ovarian carcinoma." (PMID 24244610, 2013).
silicosis (3 papers, 2010 to 2024). Silicosis is a respiratory disease caused by breathing in (inhaling) silica dust. "Compared with mice administered control Ab, IL-17-neutralized silicosis mice displayed significantly increased Foxp3 mRNA expression at all three time-points (P < 0.05)." (PMID 25091058, 2014). "The percentage of peripheral blood CD4+CD25+ Foxp3+ Treg cells is slightly lower in silicosis patients (SILs) compared with healthy donors (HD) and the function of Treg cells in SILs is less significant than in HDs." (PMID 21072213, 2010). "Treg cells are identified in the development of silicosis; however, the mechanism of CD4+CD25+Foxp3+ Treg cells to regulate immune homeostasis is still poorly understood in silicosis." (PMID 21072213, 2010).
spleen disease (3 papers, 2014 to 2021). "We investigated blood and spleen FOXP3+ Tregs in Chinese fishermen with lifelong exposure to Schistosoma japonicum and various degrees of liver and spleen disease." (PMID 26731721, 2016).